CCND1 (cyclin D1)
Diseases named in the same sentence as CCND1 in open-access papers (continued):
Sharing a sentence is not in itself a finding about the gene and the disease.
chondrosarcoma (6 papers, 2011 to 2024). A malignant cartilaginous matrix-producing mesenchymal neoplasm arising from the bone and soft tissue. "Our data revealed a significant increase in cMyc (MYC) and cyclin D1 expression after both X-rax and C-ion IR in chondrosarcoma cells." (PMID 38892366, 2024). "Altogether, these data indicate that AG1478-induced arrest of chondrosarcoma cells in G0/G1 phase involves downregulation of cyclin D1 expression and upregulation of p27kip1 tumor suppressor gene." (PMID 31139331, 2019). "We found that cyclin D1 is expressed at high amount in chondrosarcoma cells compared to primary chondrocytes, indicating that the expression of cyclin D1 is up-regulated in chondrosarcoma cells." (PMID 31139331, 2019). "In well-differentiated lipomatous tumors and in chondrosarcomas, CCND1 was frequently expressed, but all myxoid liposarcomas were negative." (PMID 21559269, 2011). "Our data indicated that cyclin D1 is up-regulated in chondrosarcoma cells." (PMID 31139331, 2019). "Interestingly, treatment of chondrosarcoma cells with AG1478 produced a strong decrease in the expression of cyclin D1." (PMID 31139331, 2019). "To elucidate the molecular mechanism involved in the arrest of chondrosarcoma cells in G0/G1 phase by AG1478, we first investigated the expression of cyclin D1 that regulates G1 phase progression, in both chondrosarcoma cells and in human primary chondrocytes." (PMID 31139331, 2019). "Given that, overexpression of cyclin D1 is correlated with tumor differentiation, poor survival, increased metastasis and resistance to certain cytotoxic drugs including tamoxifen targeting cyclin D may be considered as an effective strategy for the treatment of chondrosarcoma." (PMID 31139331, 2019). "Although in silico analysis showed that CCND1 mRNA was a validated target of miR-342-5p, the transfection of this miRNA did not clearly affect CCND1 protein expression in chondrosarcoma cell lines." (PMID 34070455, 2021). "Interestingly, treatment of chondrosarcoma cells with AG1478 decreased the expression of cyclin D1 and induced that of the CKI, p27kip1, suggesting that AG1478 inhibits cell proliferation through dowregulation of cyclin D1 and upregulation of p27kip1." (PMID 31139331, 2019).
Cirrhosis (6 papers, 2012 to 2023). A chronic disorder of the liver in which liver tissue becomes scarred and is partially replaced by regenerative nodules and fibrotic tissue resulting in loss of liver function. "It has also been suggested that CCND1 variants may be positively correlated with the precancerous cirrhosis of hepatocarcinogenesis." (PMID 29298665, 2018). "Overall, critical genes encoding for positive cell cycle progression factors (CCND1, CDK1, CDK2, E2F3, EIF4E, and MDM2) were found significantly up-regulated in HCV-cirrhosis with HCC." (PMID 22792259, 2012). "There is little information available regarding the relative expression of EGFR and cyclin D1 on HCC that develops in livers with and without cirrhosis." (PMID 38414954, 2023).
dyslipidemia (6 papers, 2015 to 2025). "Additionally, Il18−/− mice with dyslipidemia, NAFLD, and NASH showed inhibition of the Wnt signaling pathway, reduced expression of cyclin D1 (Ccnd1), and disturbances in the circadian rhythm." (PMID 38139000, 2023). "The results indicated that quercetin had an excellent binding activity with many targets, including CCND1, HIF1A, MYC, AKT1, and EGFR; therefore, it might be a key compound for the effect against dyslipidemia." (PMID 35722157, 2022).
endometrial stromal sarcoma (6 papers, 2020 to 2025). "Moreover, high-grade endometrial stromal sarcomas are typically positive for cyclin D1, BCOR, and CD117/c-kit." (PMID 40150134, 2025). "Given the presence of a mass attached to the uterus and the diffuse positivity for cyclin D1 and KIT, a diagnosis of high-grade endometrial stromal sarcoma was initially favored." (PMID 39777304, 2024). "Molecular biologically, endometrial stromal sarcomas with BCOR rearrangement bear common MDM2 amplification and activation of the cyclin D1-CDK4 pathway by CDK4 amplification by cyclin D1 protein overexpression or CDKN2A deletion." (PMID 35242139, 2022). "Endometrial stromal sarcoma was excluded in this case by negative immunostaining to CD10, ER, CD99, and Cyclin-D1 primary antibodies." (PMID 39020398, 2024).
Hepatic steatosis (6 papers, 2013 to 2025). Steatosis is a term used to denote lipid accumulation within hepatocytes. "Amongst the top Toxicity functions was hepatic steatosis (p = 6.99x10-4) with associated genes including Acaca, Cbs, Ccnd1, Cyp4a11, Ddc, Gstp1, Insig2, Por and Rorc." (PMID 26968002, 2016). "Importantly, cyclin-D1-deficient mice develop hepatic steatosis, possibly because of overactivation of PPARγ." (PMID 36091143, 2022). "After feeding for 1-wk, HFDHA0.5-fed GF zebrafish had reduced hepatic steatosis compared to HFD-fed zebrafish and reduced relative mRNA expression of Cyclin D1 (P < 0.05)." (PMID 35145984, 2021). "Based on these data, decreased serum PRL levels at ZT12 under SJL might inhibit hepatic CCND1 levels through MAPKs, leading to the activation of lipogenic enzymes (i.e., FASN and ACC) and hepatic steatosis." (PMID 40462123, 2025). "In addition to its role in cell cycle progression, the high expression of Cyclin D1 in NAFLD and livers with microsteatosis suggests its possible importance in fatty liver diseases and lipid metabolism." (PMID 35145984, 2021).
invasive ductal carcinoma (6 papers, 2011 to 2025). "The overexpression of cyclin D1 has been inversely associated with tumor grade and positively associated with the ER and PR status in invasive ductal carcinoma." (PMID 40231553, 2025). "Using techniques fluorescent in situ hybridization (FISH) and IHC, researchers observed that CCND1 had increased amplification in high-grade infiltrating ductal carcinoma in comparison to low-grade infiltrate ductal carcinoma." (PMID 33920506, 2021). "The present study illustrates the existence of a heterogeneous distribution of Ki-67 and Cyclin D1 expression within and among invasive ductal carcinomas (IDC) patients." (PMID 34394279, 2021). "Furthermore, an enhanced expression of cyclin D1 was also observed in 67.5% of invasive ductal carcinoma cases, where it was strongly correlated with estrogen receptor (ER) and progesterone receptor (PR) expression." (PMID 33920506, 2021). "But the labelling index of cyclin D1 correlated with the pathological stage of the disease in invasive lobular carcinomas but not in invasive ductal carcinomas." (PMID 21410943, 2011). "However, no significant prognostic impact of cyclin D1 expression has been found among ERα-negative cases, and the reverse relationship was demonstrated for cyclin D1 overexpression in invasive ductal carcinoma." (PMID 36975536, 2023).
leiomyoma (6 papers, 2019 to 2023). A well-circumscribed benign smooth muscle neoplasm characterized by the presence of spindle cells with cigar-shaped nuclei, interlacing fascicles, and a whorled pattern. "Another study demonstrated that WNT4 was significantly overexpressed in leiomyoma intermediate cells, inducing cell proliferation through Akt-dependent β-catenin activation, and resulting in the induction of pro-proliferative genes such as cyclin D1 and c-Myc." (PMID 36835153, 2023). "Most of the leiomyoma DEGs were found upregulated in F compared to the MF or M; however, some genes, including CDKN1A, L1CAM, SLC7A5, CCND1, IGF1R, and PTHLH, were only increased in MF vs. M and F vs. M comparisons." (PMID 33807176, 2021). "In a recent study, miR-29c, miR-200c, and miR-93 3 were reported to regulate cell proliferation of leiomyoma via their effects on key cell cycle regulatory proteins including E2F transcription factor 1(E2F1), Cyclin D1 (CCND1), and CDK2 in vitro." (PMID 31159158, 2019). "The involvement of many proteins such as FN1, COL1A1, BMP7, CCND1, EZH2, HMGA2, AhR, and E2F1 shown in the protein–protein interaction networks are well known in leiomyoma pathogenesis; others, such as SOX2, REN, PPARG, ABCB1, and NR3C1 are novel and require further investigation." (PMID 36835153, 2023).
oncocytomas (6 papers, 2010 to 2022). "It was recently proposed that oncocytomas could be subdivided into two types: type 1, displaying a diploid karyotype and CCND1 rearrangement, and type 2, exhibiting instead loss of certain chromosomes (namely, 1, Y but also X, 14 and 21)." (PMID 35269747, 2022). "Moreover, different permutations of Cyclin D1 expression levels and rearrangement of the CCND1 locus can help differentiate oncocytomas and chromophobe renal cell." (PMID 22973552, 2012). "This tumor sample also lacked the cytogenetic features typical of sporadic oncocytomas, such as loss of chromosome 1, deregulation of CCND1, and over-expression of chromosome 19 genes." (PMID 21162720, 2010). "As it is the locus of the CCND1 gene (cyclin D1), it has been subsequently found that many of these likely represent rearrangements involving CCND1, and emerging data suggest that oncocytomas harboring such rearrangements may represent a distinctive tumor subset." (PMID 29090117, 2017). "Interestingly, most of the cyclin D1-positive oncocytomas were solitary, whereas there was a considerable rate of multifocality in the cyclin D1-negative patients." (PMID 29090117, 2017).
oropharyngeal squamous cell carcinoma (6 papers, 2012 to 2017). "The overexpression of Cyclin D1 has been found in a variety of tumors types, including breast, oral and oropharyngeal squamous cell carcinoma and CRC." (PMID 25202365, 2014). "Our preliminary results have demonstrated cyclin D1 overexpression is a potential prognostic marker of primary oropharyngeal squamous cell carcinoma." (PMID 23672832, 2013). "Rainsbury’s study indicated that nuclear cyclin D1 may be a prognostic biomarker of survival in oropharyngeal squamous cell carcinoma." (PMID 24602161, 2014).
papilloma (6 papers, 2010 to 2014). A benign epithelial neoplasm that projects above the surrounding epithelial surface and consists of villous or arborescent outgrowths of fibrovascular stroma. "We conclude that gene copy number changes, somatic mutations, and alterations in tissue composition in papillomas and carcinomas account for the loss of the Ccnd1, Hras1, and Lgr5 eQTL and likely are responsible for the loss of many other eQTL seen in normal skin." (PMID 21244661, 2011). "In Papillomas, Cyclin D1 exhibited a mean 11.42% (11.42% ± 10.17%) co-expression rate with Cytokeratin 8/18 compared with a mean 2.50% (2.50% ± 3.24%) co-expression rate with Cytokeratin 5/6 (p < 0.01)." (PMID 23327593, 2013). "Conversely, if the percentage of the Cyclin D1 expression was below 4.20% and posirive for CK 5/6 expression, a diagnosis of papilloma was made." (PMID 23327593, 2013). "In the papillomas, Cyclin D1 was predominantly expressed in CK 8/18 positive cells with limited expression CK 5/6 positive cells." (PMID 23327593, 2013).
pituitary tumor (6 papers, 2015 to 2025). A benign or malignant neoplasm affecting the pituitary gland. "The observation of increased cyclin D1 protein expression in association with down regulation of miR-15a and miR-16-1 in pituitary tumours from Men1+/− mice, suggests that cyclin D1 is a putative target of miR-15a and miR-16-1 in these Men1-associated pituitary tumours." (PMID 30389902, 2018). "In pituitary tumors, cyclin D1 (CCND1) is particularly important, as it plays a role in the proliferation, progression, and potential aggressiveness of these tumors." (PMID 40869149, 2025). "Cyclin D1 has a bearing on cell proliferation, recurrence, and aggressive behavior of pituitary tumors." (PMID 34295309, 2021). "Previous studies reported that Cur inhibited cell proliferation correlations with the downregulation of cyclin D1 expression in various cancer types, such as pancreatic, prostate, breast and pituitary tumor cells in both in vitro and in vivo models." (PMID 32545675, 2020). "This revealed a significant increase in CCND1 mRNA levels in Men1+/− pituitary tumours (n = 5), when compared to normal pituitaries (n = 5) from WT mice (2.6-fold, P < 0.0005)." (PMID 30389902, 2018). "In conclusion, we demonstrate that miR-15a and miR-16-1 are both downregulated in pituitary tumours of Men1+/− mice and that this decrease in expression correlates with an increase in cyclin D1 expression." (PMID 30389902, 2018).
synovial sarcoma (6 papers, 2017 to 2024). "Expression profiles of mouse synovial sarcomas were also analyzed, and enriched genes within Cyclin D1, PTEN, and β-catenin pathways were also found to be upregulated." (PMID 32019274, 2020). "All of the four synovial sarcoma cell lines also expressed cyclin D1, pRb, Rb, and Bcl-xL." (PMID 29670090, 2018). "Sorafenib inhibits cyclin D1 expression in NB4 acute promyelocytic leukemia cells, SW982, and HS-SY-II synovial sarcoma cells." (PMID 38527038, 2024). "Consistent with the inhibition of G1-to-S phase progression, we found decreased cyclin D1 expression and decreased phosphorylation of CDK4 and CDK2 in synovial sarcoma cells in response to SAHA, LBH-589, and PXD101." (PMID 29100385, 2017). "However, Igf1, which is downstream of the Cyclin D1 pathway, was upregulated both in tumors and eMCs expressing SS18-SSX1, which might be important for drug resistance in synovial sarcoma treatment." (PMID 32019274, 2020).
uterine fibroids (6 papers, 2016 to 2024). "In uterine fibroids, TRIM9 is overexpressed and regulates cyclin D1, survivin, lysed caspase 3 and nuclear NF‐κB to enhance cell proliferation, reduces apoptosis and significantly promotes the growth of uterine fibroids." (PMID 38263865, 2024). "And then, the expression of Cyclin D1 and c-Myc was decreased, and the proliferation of uterine leiomyoma cells was inhibited." (PMID 35113040, 2022). "miR-29 inhibitors promoted protein expression of STAT-3, Cyclin D1, and c-Myc compared with the anti-NC control (P < 0.01), and miR-29 inhibitors promoted cell proliferation in uterine leiomyoma cells (P < 0.05)." (PMID 35113040, 2022). "CCND1, an important regulator of cell cycle progression and proliferation, is known to drive tumorigenesis and was also found upregulated in uterine fibroids." (PMID 33807176, 2021). "Using MCODE, we found that STAT3, VEGFA, CCND1, and other genes were the hub genes of uterine leiomyoma, proving that they might play a significant role in the pathogenesis and progression uterine leiomyoma." (PMID 35113040, 2022). "When miR-29 was not inhibited, it could bound to STAT3 and led to the degradation of STAT3, thereby reducing the expression of Cyclin D1 and c-Myc and inhibiting the proliferation of uterine leiomyoma cells." (PMID 35113040, 2022). "One research showed that STAT3 could increase the expression of Cyclin D1 and c-Myc, and promote the proliferation of uterine leiomyoma cells." (PMID 35113040, 2022). "We have highlighted the differential expression of 3 genes (BDNF, CCND1, and VWF) in our results that we think could play key roles in uterine fibroid etiology or pathogenesis." (PMID 36066972, 2022). "This study provides insight into a mechanism whereby Cd, a metalloestrogen, induced cell proliferation in hormonally responsive human uterine leiomyoma (ht-UtLM) cells, and the molecular basis of a FOXM1 and Cyclin D1-regulated event downstream of MAPK induced by Cd." (PMID 33818655, 2021). "Cd concurrently increases the expression of FOXM1 and Cyclin D1 downstream of MAPK44/42, which in turn upregulates the kinase Aurora B, leading to Histone H3 phosphorylation at serine 10 site, and resulting in human uterine leiomyoma cell mitosis." (PMID 33818655, 2021).
Wilms tumor (6 papers, 2014 to 2023). An embryonal neoplasm characterized by the presence of epithelial, mesenchymal, and blastema components. "Most cases of Wilms tumor (epithelial component) also demonstrated diffuse and often strong positivity for Cyclin D1." (PMID 30736802, 2019). "Synergistically overexpression of WT1 and STAT3 in tumor development, including Wilms’ tumor, increases the expression level of STAT3 target genes, including cyclin D1 and Bcl-xL, resulting in an advantage of cell proliferation." (PMID 25474318, 2014). "Cyclin D1 may be recommended as an immunohistochemical marker in the differential diagnosis of CCS and Wilms tumor." (PMID 35147974, 2022). "No immunoreactivity for cyclin D1 was observed in the other SRBCTs, including RMS (regardless of subtype), LL and Wilms’ tumor." (PMID 34943491, 2021).
acute lymphoblastic leukemia (5 papers, 2016 to 2022). Leukemia with an acute onset, characterized by the presence of lymphoblasts in the bone marrow and the peripheral blood. "It was hypothesized that CCND1 gene polymorphism affects acute lymphoblastic leukemia (ALL) development, prognosis and may relate to methotrexate cytotoxicity." (PMID 33112552, 2020). "For osteonecrosis of the femoral head, aberrant expression of CCND1 has been also found in the patients with osteonecrosis of the femoral head induced by systemic lupus erythematosus, and ESR1 may involve the osteonecrosis development of the children with acute lymphoblastic leukemia." (PMID 35035862, 2022).
B-cell neoplasm (5 papers, 2011 to 2023). A group of heterogeneous lymphoid tumors generally expressing one or more B-cell antigens or representing malignant transformations of B-lymphocytes. "MCL is a mature B-cell neoplasm with heterogeneous clinical behavior molecularly characterized by the constitutive overexpression of cyclin D1 and deregulation of different signaling pathways." (PMID 37718438, 2023). "In general, B-cell neoplasms carrying rare translocations involving CCND1 and Ig kappa or Ig lambda, like reported here, are diagnosed as MCL." (PMID 21457541, 2011).